STAT3 (signal transducer and activator of transcription 3)
Diseases named in the same sentence as STAT3 in open-access papers (continued):
Sharing a sentence is not in itself a finding about the gene and the disease.
prostate carcinoma (continued). "In addition, a recent report showed that inhibition of IL-6/STAT3 signaling in a phosphatase and tensin homolog (PTEN)-deficient prostate cancer model promotes cancer progression." (PMID 28264478, 2017). "Scholars have argued that the CCL2–p-STAT3 pathway stimulates prostate cancer metastasis and progression, and may be critical in future efforts to develop new therapeutic approaches for treating prostate cancer." (PMID 28157698, 2017). "Capz inhibited both constitutive and induced STAT3 activation in human prostate carcinoma cells." (PMID 27458171, 2017). "In addition, IL-6-driven metastasis of prostate cancer was predominantly mediated by STAT3 signaling." (PMID 28783760, 2017). "Likewise, treatment of DU145 prostate cancer cells with the STAT3 inhibitor galiellalactone reduces the frequency of ALDH-positive CSCs." (PMID 26880966, 2016). "However, constitutive activation of STAT3 has been observed in many tumor types, including prostate cancer." (PMID 26683224, 2016). "In addition, icariside II was proved to reduce the level of STAT3 in MDA-MB-231 (breast adenocarcinoma) and DU145 (prostate carcinoma) cells, in which STAT3 is constitutively active." (PMID 27649234, 2016). "Constitutively activation of STAT3 is found in approximate 70 % of the solid malignancies, including hematological malignancies as well as diverse solid tumors such as head and neck, breast, lung, gastric, hepatocellular, colorectal and prostate cancers." (PMID 27435207, 2016). "Since GL inhibits both STAT3 and NF-κB transcriptional activities, and both transcription factors participated in the progression of cell cycle in cancer cells, we were interested in studying the effect of GL on the cell cycle of prostate cancer cells." (PMID 26683224, 2016). "Notably, re-expression of STAT3 in human PC3 prostate carcinoma cells, which lack STAT3 expression, led to significantly decreased cell numbers and reduced foci formation." (PMID 26198641, 2015). "It is of note that STAT3 inhibition abrogate IL-6-dependent conversion of ALDH (low) prostate cancer cells to ALDH(high) whereas STAT3 activation induces a melanoma-initiating cell phenotype that could favor chemotherapy resistance and relapse." (PMID 26486080, 2015). "Since STAT3 can regulate Bcl-3 expression in prostate cancer, we wondered whether STAT3 and Bcl-3 expression are also linked in MCF-7 cells." (PMID 26515727, 2015). "STAT3 is also involved in the response to tyrosine kinase inhibitors sunitinib and axitinib, in patients with metastatic renal cell carcinoma, and to second-generation androgen receptor inhibitor enzalutamide in patients with advanced prostate cancer." (PMID 28031890, 2015). "Finally, we demonstrated the feasibility of using TLR9-targeted siRNA delivery to block RELA- and STAT3-dependent prostate cancer cell self-renewal in vivo." (PMID 26046794, 2015). "Finally, silencing of RELA or STAT3 specifically in TLR9+ tumor-propagating cells inhibits growth of established prostate cancers in vivo." (PMID 26046794, 2015). "However, there is compelling evidence on the role of NF-κB and STAT3 in prostate cancer cell proliferation, survival and androgen-independence." (PMID 26046794, 2015). "In this study, we identified several genes including the cytokines Il-6, Tgfb2, Cxcl1, and Ctgf, metallopeptidases Mmp13, Adamts1, Adamts4, and Adamts5, and transcription factors Junb, Fos, Stat3 and Cebpb that were up-regulated in osteoblasts as a result of prostate cancer–osteoblast interactions." (PMID 27600237, 2015). "Our results showed that Stattic effectively eliminated the ALDHhigh subpopulation in PC3M-1E8 cells and primary cell cultures from different clinical prostate cancer samples, even at a low doses, suggesting that this subpopulation of prostate TICs is sensitive to STAT3-mediated inhibition." (PMID 25261365, 2014).
prostate carcinoma (continued). "While the role for STAT3 in promoting the progression of many solid and hematopoietic malignancies is well established, this review will focus on the importance of STAT3 in prostate cancer progression to the incurable metastatic castration-resistant prostate cancer (mCRPC)." (PMID 24722453, 2014). "Moreover, blockade of STAT3 signaling was significantly effective in eradicating the tumor-initiating and bulk tumor cancer cell populations in both prostate cancer cell-line xenograft model and patient-derived tumor xenograft (PDTX) models." (PMID 25261365, 2014). "If LLL12, a novel pSTAT3 inhibitor, is applied to prevent STAT3 from phosphorylation, the stemness of prostate cancer cells is inihibited, resulting in significant reduction of cancer cell proliferation in primary cultures from patients with high Gleason grades." (PMID 24618337, 2014). "Induction of RKIP expression inhibits the activation of signal transducer and activator of transcription 3 (STAT3), NF-κB pathway, and downstream Yin Yang 1 (YY1) as well as antiapoptotic gene products, causing induction of apoptosis in breast and prostate cancer cells." (PMID 25147739, 2014). "STAT3 is cleaved by caspases in prostate cancer cells generating multiple STAT3 protein fragments." (PMID 24810717, 2014). "Further analysis of functional enrichment of STAT3 targets in prostate cancer showed these target played an important role in various cellular process regulations implicated in carcinogenesis, for example, cell surface binding and the activity regulation of different kinds of proteinases." (PMID 24205155, 2013). "Hence, STAT3 has been identified as an attractive target for prostate cancer, where its activity is inherently activated." (PMID 24103426, 2013). "Our results also showed that DU-145 and PC-3 PCa cells treated with 160 μM and 75 μM of piperine dose respectively also resulted in the downregulation of NF-kB and phosphorylated STAT-3 expression levels, underscoring the anti-cancer effects of piperine in prostate cancer cells." (PMID 23824300, 2013). "Functional enrichment analysis of STAT3 targets in prostate cancer." (PMID 24205155, 2013). "Finally, recent data suggests that EZH2 regulated by STAT3 is correlated to the pathological stage and progression of prostate cancer." (PMID 24772452, 2013). "Increased STAT3 activity is frequently found in a wide variety of human tumors, including hematopoietic malignancies (leukemia, lymphoma, and multiple myeloma) as well as solid tumors (such as head and neck, breast, and prostate cancers)." (PMID 23531921, 2013). "Interestingly, we found STAT3 appeared in 18 FFLs of prostate cancer, which was significantly enriched compared to those in normal prostate tissue (chi-square test, p-value = 2.6×10−12) and in pan-cancer (chi-square test, p-value = 3.8×10−3)." (PMID 24205155, 2013). "However, androgen dependent prostate cancer cells (LNCaP) were found to be more sensitive to piperine treatment due to downregulation of multiple targets such as AR, NF-kB and STAT-3 expression in these cells." (PMID 23824300, 2013). "Interestingly, treatment of LNCaP, PC-3 and DU-145 prostate cancer cells with piperine resulted in reduced expression of phosphorylated STAT-3 and Nuclear factor-κB (NF-kB) transcription factors." (PMID 23824300, 2013). "In this context, the signal transducer and activator of transcription 3 (STAT3) signaling pathway has been validated as a promising therapeutic target in metastatic prostate cancer: this protein is aberrantly activated in prostate cancer and contributes to the promotion of metastatic progression." (PMID 24260381, 2013). "Thus, our findings suggest that scoparone acts at least partly through inhibition of constitutively activated STAT3, and that it represents a novel candidate for a chemotherapeutic agent against prostate cancer." (PMID 24260381, 2013).
prostate carcinoma (continued). "Moreover, we discovered more than 24% of the target of STAT3 found in pan-cancer also appeared in prostate cancer." (PMID 24205155, 2013). "This study was undertaken to investigate the anti-tumor activity of scoparone against DU145 prostate cancer cells and to determine whether its effects are mediated by inhibition of STAT3 activity." (PMID 24260381, 2013). "In addition, S1P and S1P-containing HDL activate STAT3 signaling in ventricular cardiomyocytes and in prostate cancer cells." (PMID 22606352, 2012). "Our results demonstrate that M-HIFU can inhibit STAT3 activities, and when combined synergistically with surgery, may provide a novel and promising strategy for the treatment of prostate cancers." (PMID 22911830, 2012). "Thus, our findings suggest that BA can be a potent anti-angiogenic agent by targeting STAT3/HIF-1α/VEGF signaling for prostate cancer therapy." (PMID 21731766, 2011). "A transgenic mouse model in which PKCε was expressed specifically in the mouse prostate leads to the occurrence of prostate intraepithelial neoplasia (PIN) through STAT3 activation, suggesting that PKCε may be involved in prostate cancer development." (PMID 22110995, 2011). "We therefore examined whether activation of STAT3 via IL-6 stimulation led to repression of Necdin expression in the prostate cancer cell lines DU145 and PC3." (PMID 22046235, 2011). "Targeting the STAT3 pathway in prostate cancer stem cell-like cells with natural product derived compounds may be a promising therapeutic approach for the development prostate cancer drugs." (PMID 21779382, 2011). "Finally, PEITC is capable of suppressing multiple oncogenic signaling pathways that are hyperactive in human prostate cancer, including nuclear factor-κB (NF-κB), Akt, signal transducer and activator of transcription 3 (STAT3), and androgen receptor." (PMID 22039516, 2011). "Moreover, STAT3 has been suggested to be involved in IL-6-induced resistance to β-lap in prostatic cancer cells." (PMID 21738692, 2011). "However, the Oncomine and GEO data further support the observation that expression of both Sox1 and Stat3 are key genes regulating the progression of prostate cancer." (PMID 20929579, 2010). "Finally, both Sox1 and Stat3 were found to have increased expression in relation to the progression of prostate cancer in humans." (PMID 20929579, 2010). "Finally, using Oncomine, it was determined that more aggressive metastatic prostate cancers in humans also have higher levels of both Stat3 and Sox1." (PMID 20929579, 2010). "STAT3 activation plays a critical role in prostate cancer cell invasion." (PMID 19484134, 2009). "By testing human prostate cancer cell lines, we have found that glucosamine dose-dependently suppresses proliferation and increases apoptosis, and these anti-proliferative effects depend on the status of STAT3 pathway in these cells." (PMID 19744341, 2009). "STAT3 is activated in many different cancers including colon, breast and prostate cancers." (PMID 19744341, 2009). "Activation of STAT3 signaling pathway is critical for prostate cancer invasion." (PMID 19484134, 2009). "Some members of the STAT protein family, particularly STAT3 and STAT5, regulate several oncogenic processes such as proliferation, survival, angiogenesis and immune response, and activated STAT3 pathway is frequently found in different human tumors including prostate cancer." (PMID 19744341, 2009). "One possible mode by which IL-6 may influence progression of prostate cancer to the hormone-refractory state is by activating the IL-6 receptor/JAK1/STAT3 pathway, resulting in differentiation and inhibition of apoptosis." (PMID 17595657, 2007). "In addition, in vitro studies have demonstrated that IL-6-dependent activation of the JAK/STAT3 pathway is accompanied by transition from hormone-sensitive to hormone-insensitive prostate cancer cell growth." (PMID 17595657, 2007).
prostate carcinoma (continued). "Indeed, the increase in proliferation rate observed in prostate cancer cell line models in response to IL-6 has been demonstrate to be via activation of STAT3." (PMID 17595657, 2007). "Moreover, activated STAT3 is believed to play a key role in androgen receptor activation in the absence of androgens, one explanation of hormone refractory growth of prostate cancer." (PMID 17712417, 2007). "In summary, despite the large number of in vitro functional reports implying a role of IL-6R/JAK/STAT3 pathway in prostate cancer progression there appears to be little data confirming the role of this pathway in the development of clinical hormone-refractory prostate cancer." (PMID 17595657, 2007). "Interestingly, in certain myeloma and prostate cancer cell lines, IL-6 has been identified as the main cytokine responsible for Stat3 activation induction." (PMID 17925034, 2007). "Recent studies suggest that aberrant STAT3 signalling may play an important role in the carcinogenesis of prostate cancer." (PMID 16804520, 2006). "Our results gives possible insight into the mechanism of retinoid insensitivity, and might also indicate that treatment of prostate cancer with STAT3 inhibitors and with retinoids may be beneficial." (PMID 15647107, 2005). "However aberrant signaling by STAT3 has been noted in many types of malignancies, such as myeloma, head and neck cancer, breast cancer, and prostate cancer." (PMID 15647107, 2005). "Because we are interested in how persistently-activated STAT3 changes the cellular phenotype to a malignant one in prostate cancer, we used expression vectors containing a gene for constitutively-activated STAT3, called S3c, into NRP-152 rat and BPH-1 human benign prostatic epithelial cells." (PMID 15647107, 2005). "For example STAT3 protects prostatic cancer cells from apoptosis induced by T lymphocytes." (PMID 16001973, 2005). "Activated STAT3 is thought to play an important role in prostate cancer (PCA) progression." (PMID 15647107, 2005). "Furthermore, it has been shown that angiotensin II induces the phosphorylations of mitogen-activated protein kinase (MAPK) and signal transducer and activator of transcription 3 (STAT3) in prostate cancer cells." (PMID 15813980, 2004). "Thus, TLR9/LIF/STAT3 signaling-targeting oligonucleotide-based inhibitors (e.g., CpG-STAT3dODN) may present novel prospects for prostate cancer immunotherapy." (PMID 40727443, 2025). "However, whether Osthole exerts its effects via PRLR and JAK2/STAT3 signaling in prostate cancer remains unclear." (PMID 40978029, 2025). "Similarly, ovarian and prostate cancers exhibit increased STAT3 activity." (PMID 40166646, 2025). "Thus, targeting the JAK2/STAT3 pathway offers a promising strategy for prostate cancer therapy." (PMID 40978029, 2025). "Thus, CA might act as a therapeutical application against prostate cancer by targeting the IL-6/JAK/STAT3 signaling axis." (PMID 39574470, 2024). "Furthermore, morusin could also decrease the activity of STAT3 in inducing the apoptosis in prostate cancer cells." (PMID 38694910, 2024). "According to research, canine prostate carcinogenesis is also involved in the overexpression of STAT3 and downregulation of PTEN, and both indicators may be associated with the histological subtypes of prostate cancer and the degree of differentiation of neoplastic cells." (PMID 37009802, 2023). "Therefore, oligonucleotide-based inhibitors (e.g., CpG-STAT3dODN) targeting TLR9/LIF/STAT3 signaling may offer new opportunities for prostate cancer immunotherapy." (PMID 36365103, 2022). "Furthermore, previous study revealed a potential novel role for SHMT2 as a downstream element of the STAT3 signaling pathway, and this molecular mechanism may be responsible for the transition of prostate cancer towards a more aggressive phenotype." (PMID 36077112, 2022).
prostate carcinoma (continued). "Interestingly, in tumours where Cad11 or N-cadherin promotes metastasis (e.g., breast and prostate cancers,), then inhibition of Cad11 would induce apoptosis (through Stat3 inhibition) in metastatic tumour cells specifically, since normal cells would have low E2F activity, hence would be spared." (PMID 36010614, 2022). "Emerging studies revealed that PTEN loss in prostate cancer resulted in an immunosuppressive tumor microenvironment through the activation of the Janus kinase 2 (JAK2)–signal transducer and activator of transcription 3 (STAT3) pathway and the subsequent secretion of immunosuppressive chemokines." (PMID 33874915, 2021). "ASC-J9 could also inhibit the proliferation and metastasis of prostate cancer by regulating pSTAT3-C-C motif chemokine-2 (CCL2) signal transduction through an AR-dependent pathway via inhibiting the expression of the protein inhibitor of STAT3 (PIAS3)." (PMID 34295247, 2021). "Furthermore, an osteoblastic phenotype of prostate cancer bone metastases is associated with an activation of the STAT3 signaling but not with AKT activation." (PMID 34064589, 2021). "Importantly, STAT3 is also revealed here to be a targetable vulnerability that disables the growth of bone metastatic PCa, suggesting that STAT3 inhibitors such S3I-20138, which appears well-tolerated in pre-clinical studies, and have potential in the prostate cancer clinic." (PMID 33526787, 2021). "However, to delineate the importance of IL-10 in the immunosuppressive effect mediated by MDSCs through STAT3, Hellsten and colleagues have demonstrated that inhibition of STAT3 using galiellalactone prevented the generation of MDSC-like cells from treated prostate cancer ex vivo." (PMID 32931721, 2020). "In another study, STAT3 small interfering (si)RNA conjugated to cpG oligonucleotide agonist of TLR9 targeted tumor associated myeloid cells by silencing STAT3, thus leading to a potent antitumor immune response in multiple tumor mouse models and prostate cancer patients." (PMID 32509781, 2020). "In addition, RANKL is known to enhance EMT in prostate cancer through the STAT3/LIV-1 axis." (PMID 31952344, 2020). "Interestingly, a recent study provided evidence about a key role of the upregulation of miR-424 in impaired ubiquitination and degradation of Stat3, through the targeting of the E3 ubiquitin ligase COP1, leading to accumulation and activation of Stat3 in prostate cancer cells." (PMID 31366128, 2019). "Previous studies on prostate cancer FFPE tissues highlighted a different STAT3 PTM pattern in PCa specimens at different clinical stages, so we hypothesize that STAT3 PTMs may be involved in PCa progression, and can modulate different signal transduction pathways depending on the triggering stimuli." (PMID 31013746, 2019). "These compounds inhibited the proliferation of prostate cancer cells by repressing the overexpression of miRNA-372, inhibiting inflammation pathways such as the NF-kappaB-dependent pathway, inducing apoptosis, acting as a poroteasome inhibitor, and inhibiting STAT3 activity." (PMID 29495626, 2018). "Indeed, our group has previously identified two other STAT3 blockers namely nimbolide and formononetin that may function through identical molecular mechanism(s) in prostate cancer and multiple myeloma models respectively." (PMID 30413072, 2018). "In prostate carcinoma, STAT3 may play a critical role in maintaining the cancer stem cells (CSC)." (PMID 29854771, 2018).